BMP7 (bone morphogenetic protein 7)
Diseases named in the same sentence as BMP7 in open-access papers (continued):
Sharing a sentence is not in itself a finding about the gene and the disease.
chronic kidney disease (15 papers, 2010 to 2025). Impairment of the renal function secondary to chronic kidney damage persisting for three or more months. "Bmp7, found upregulated in infected samples, has been described as a stromal cell-derived cytokine that antagonizes fibrosis and can reverse chronic kidney disease." (PMID 37539049, 2023). "While BMP-7 expression levels are suppressed in various chronic kidney diseases, BMP-7 and its agonists have been actively investigated to ameliorate kidney fibrosis or facilitate kidney regeneration." (PMID 36558936, 2022). "SD cells form a subset of cells with multilineage potential and known renoprotective properties that attenuate chronic kidney disease (CKD) through an increase of BMP-7 expression." (PMID 33401654, 2021). "A large variety of evidences shows an antifibrotic role of BMP-7 in chronic kidney disease, and this effect is largely mediated via counterbalancing the profibrotic effect of TGF-β1." (PMID 31007700, 2019). "Hyperphosphatemia and vascular calcification are frequent complications of chronic renal failure and bone morphogenetic protein 7 (BMP7) has been shown to protect against development of vascular calcification in uremia." (PMID 29304096, 2018). "A large variety of evidence shows an anti-fibrotic role of BMP-7 in chronic kidney disease, and this effect is largely mediated via counterbalancing the profibrotic effect of TGF-β." (PMID 25954203, 2015). "Bone morphogenetic protein 7 (BMP7) has been suggested to play a protective role against kidney injury in chronic kidney disease." (PMID 23573468, 2012). "Bone Morphogenetic Protein (BMP)-7 is protective in different animal models of acute and chronic kidney disease." (PMID 21080950, 2010). "In chronic kidney disease and fibrosis, BMP7 levels are decreased, suggesting a contribution to fibrosis that we speculate may be due, in part, to decreased endothelial Id levels and capillary rarefaction." (PMID 24516656, 2014). "This high dose of BMP-7 may have inhibited the systemic administration as a therapeutic option for chronic kidney disease." (PMID 21080950, 2010). "Additionally, BMP7 decreased oxidative stress in a diabetic chronic kidney disease animal model." (PMID 40076659, 2025). "Arterial stiffness, common in chronic kidney disease (CKD), may be linked to an imbalance in BMP-2 and BMP-7, leading to renal damage, hypertension, and increased pulse wave velocity (PWV) in CKD." (PMID 39070522, 2024). "Taken together, these data suggest that IL-15 reduction, as observed for the antifibrotic factors, such as BMP-7 and HGF, may be a critical event in renal fibrogenesis and in acute and chronic kidney diseases." (PMID 34769128, 2021). "Moreover, the absence of BMP7 frequently leads to renal development disorder and chronic kidney disease." (PMID 36858954, 2023).
atherosclerosis (14 papers, 2014 to 2025). A disease characterized by the build-up of fatty material and calcium deposition in the arterial wall resulting in partial or complete occlusion of the arterial lumen. "It was shown that recombinant human BMP7 inhibits atherosclerosis-associated inflammation." (PMID 37626658, 2023). "Similarly, BMP-4, BMP-10, and BMP-7 have been implicated in cardiovascular physiology and pathology, including vascular inflammation, atherosclerosis, and calcification; however, their prognostic value for systemic cardiovascular risk in patients with PAD has not been established." (PMID 40710778, 2025). "Further, we also observed reduced circulatory BMP-7 levels as atherosclerosis progressed and that the exogenous supplementation of BMP-7 significantly attenuated disease progression." (PMID 31979268, 2020). "Nevertheless, BMP7 is a gene that appears to corroborate this concept since it is described as promoter of normal osteoblast function and capable to prevent atherosclerosis." (PMID 25380738, 2014). "Similarly, elevated levels of other BMPs such as BMP4, BMP7, BMP9 were associated with atherosclerosis, hepatic cancer, and metabolic syndrome respectively." (PMID 38127951, 2023). "One study reported that exogenous BMP-7 significantly decreases plaque formation following the induction of atherosclerosis by inhibiting M1 macrophage differentiation and promoting M2 polarization, whereas macrophage depletion abolishes this beneficial effect in Apoe−/− mice." (PMID 36909186, 2023). "Interestingly, the ability to induce M2 macrophage polarization seems to be shared with other BMP ligands since BMP2 promotes the acquisition of a M2 phenotype during bone regeneration and BMP-7 treatment increases M2 differentiation and reduces inflammation and plaque formation in atherosclerosis." (PMID 31337120, 2019). "However, the role of BMP-7 in inflammatory mediation of atherosclerosis had yet to be investigated." (PMID 26824441, 2016). "Thus, LPL and BMP7, which are associated with insulin and glucose homeostasis, and MCP2 and SST, which are associated with regulation of immune system processes and cell migration, may play important roles in both the formation and regression of atherosclerosis." (PMID 30958112, 2019). "The literature on BMP-7 in macrophage polarization is new and growing; however, there are certain unanswered questions such as whether BMP-7 can inhibit the formation of foam cells; and if BMP-7 can inhibit the conversion of M2 macrophage into foam cell formation in atherosclerosis?" (PMID 31979268, 2020).
gastric cancer (14 papers, 2009 to 2023). A primary or metastatic malignant neoplasm involving the stomach. "High BMP7 expression was reported to be significantly associated with greater nodal, lymphatic and venous invasion in gastric cancer." (PMID 37688374, 2023). "The same epigenetic regulation of BMP7 was also observed in prostatic and gastric cancers where BMP7 expression is associated with a more aggressive phenotype." (PMID 24069261, 2013). "We can use BMP-7 expression as one of the strong predictors of risk of tumour recurrence in gastric cancer." (PMID 21224856, 2011). "BMP7 [Bone Morphogenic Protein] (chromosome # 8p21), a gene already implicated in PCa progression which was previously reported as methylated in an oligodendroglioma cell line and gastric cancers." (PMID 19283074, 2009). "We indicated that bone morphogenetic protein-7 (BMP7) is one of the independent prognostic markers in gastric cancer." (PMID 29396725, 2018). "In contrast, BMP-7 expression is associated with a metastatic phenotype and a poor prognosis in human gastric cancer, suggesting that BMP-7 promotes gastric cancer progression." (PMID 24137334, 2013). "From the data collected, it would be appropriate to conclude on the possible regulation of gastric cancer progression by autocrine or paracrine BMP-7 loops." (PMID 21224856, 2011). "In this study, BMP-7-positive gastric cancer was shown to be correlated with well-differentiated tumour histology." (PMID 21224856, 2011). "Immunohistochemically, in human gastric cancer, BMP-7 expression was identified in cellular membranes but also in the cytoplasm of cancer cells." (PMID 21224856, 2011). "We can use BMP-7 expression as a predictor of lymph node metastasis and postoperative outcome in gastric cancer." (PMID 21224856, 2011). "Multivariate analysis indicated that BMP-7 expression was one of the independent prognostic factors of overall survival for the patients with gastric cancer next to the depth of invasion and nodal involvement (P<0.01)." (PMID 21224856, 2011). "We immunohistochemically investigated the expression of BMP-7 in 233 gastric cancer patients to disclose the clinicopathological features of BMP-7-positive gastric cancer." (PMID 21224856, 2011). "We showed that BMP-7 expression in gastric cancer was an independent prognostic marker in accordance with results for other cancers." (PMID 21224856, 2011). "In conclusion, from the data collected, it would be appropriate to conclude on the possible regulation of gastric cancer progression by autocrine or paracrine BMP-7 loops." (PMID 21224856, 2011). "Previous studies have shown methylation of BMP7 in gastric cancers and oligodendroglioma cell lines, suggesting that silencing of BMP7 through this mechanism is not limited to PCa alone." (PMID 19283074, 2009). "Bone morphogenetic protein-7 (BMP7) is an independent prognostic marker in gastric cancer." (PMID 34885041, 2021). "In addition, BMP7 expression has been correlated with tumor recurrence in gastric cancer." (PMID 25315765, 2014). "However, to our knowledge, there have been no reports demonstrating the association between BMP-7 expression and clinicopathological factors including prognosis in gastric cancer." (PMID 21224856, 2011). "The treatment of gastric cancer cell lines with OCT4 and JDP2 inhibited the tumorigenic function of the cells by switching off BMP7." (PMID 32493501, 2020). "In this study, robust expression of the BMP-7 mRNA was identified by RT–PCR in MKN45 and MKN74 gastric cancer cell lines, which were derived from liver metastasis (data not shown)." (PMID 21224856, 2011). "Thus, the purpose of this study was to investigate BMP-7 expression by immunohistochemistry in gastric cancer and evaluate the clinical impact of BMP-7-positive gastric cancer." (PMID 21224856, 2011). "Thus, BMP-7 expression of biopsy may be informative to predict lymph node metastasis, when we should choose between endoscopic resection or gastrectomy for early gastric cancer." (PMID 21224856, 2011).
glioblastoma (13 papers, 2014 to 2025). The most malignant astrocytic tumor (WHO grade IV). "Thus, in this study, we determined the BMP7 effect on glioblastoma transmigration and migration regulations and the underlying mechanisms." (PMID 34357080, 2021). "Likewise, treatment with a BMP7 variant suppressed the tumorigenicity of stem-like glioblastoma cells and reduced angiogenesis and brain invasion." (PMID 26546412, 2015). "Initial tests with BMP7-loaded microspheres demonstrated antitumoral effects in glioblastoma models both in vitro and in vivo." (PMID 40688657, 2025). "It was shown that the Smad5 gene knockdown significantly blocks BMP7-increased p75NTR protein expression in human LN18 glioblastoma cells." (PMID 34357080, 2021). "The increase in human LN18 glioblastoma cell transmigration level of 100 ng/mL BMP7 stimulation slightly declined compared to the 50 ng/mL BMP7-treated cells, but it still higher than the untreated controls." (PMID 34357080, 2021). "The present study has found an autocrine BMP7 effect on glioblastoma transmigration and migration in human LN18 glioblastoma cells through Smad5, but not Smad1, and p75NTR signaling pathway." (PMID 34357080, 2021). "In this study, we investigated the potential role of BMP7 in glioblastoma cell transmigration and migration capabilities." (PMID 34357080, 2021). "This is due to the fact that BMP4 and BMP7 have also been found for their invasion-promoting activities in glioblastoma cells." (PMID 34357080, 2021). "It was shown that BMP7 increases the p75NTR protein expression in human LN18 glioblastoma cells in a dose-dependent manner compared to the untreated controls." (PMID 34357080, 2021). "Our findings provide new insights into the understanding and elucidation of autocrine role of BMP7 and Smad1/5 signaling in promoting the glioblastoma metastasis." (PMID 34357080, 2021). "We found a higher BMP7/pSmad5 level in clinical malignant glioma and found an autocrine effect of BMP7 on glioblastoma cell transmigration and migration." (PMID 34357080, 2021). "Recently, in addition to the tumorigenicity inhibitory activity, BMP7 has been found as another interesting role in the glioblastoma invasion promotion." (PMID 34357080, 2021). "The knockdown efficiency of BMP7-specific siRNA was examined in human LN18 glioblastoma cells, which resulted in ~70% reduction in the endogenous BMP7 expression level." (PMID 34357080, 2021). "Human LN18 glioblastoma cells were kept as the controls or treated with BMP7 (25, 50, and 100 ng/mL) for 24 h and then the transmigration capability of cells was determined by the transwell assay." (PMID 34357080, 2021). "Hepatocytes cultured on a printed array of BMP7 protein are protected from ethanol-induced apoptosis, and ethanol inhibits the morphological changes and cell adhesion induced by BMP7 exposure in cultured neuroblastoma/glioblastoma cells." (PMID 31456662, 2019). "Intracranial delivery of BMP7 to tumor xenografts generated by intracerebral injection of human glioblastoma stem-like cells significantly reduced growth, invasion and the overall mitotic index." (PMID 29799477, 2018). "BMP7 reduces tumor growth and down-regulates expression of progenitor cell biomarkers in subcutaneous and orthotopic glioblastoma xenografts." (PMID 29799477, 2018). "In glioblastoma, BMP-7 reduces cell growth, inhibits sphere formation, and decreases self-renewal capacity via canonical SMAD1, 5, and 8 signaling." (PMID 27661009, 2016). "These authors showed that BMP7 (released by neural precursor cells) stimulates a canonical BMP response in stem-like glioblastoma cells." (PMID 24877113, 2014). "Overall, the present study finds that the invasion-promoting activity of BMP7 might be an autocrine stimulation of glioblastoma and this effect could be regulated by Smad5-p75NTR signaling." (PMID 34357080, 2021). "In this BMP7 event, we further demonstrated that p75NTR could be upregulated in glioblastoma cells by Smad5 signaling." (PMID 34357080, 2021).
glioblastoma (continued). "It was shown that BMP7 could accelerate the human LN18 glioblastoma cell migration after 24 h of treatment." (PMID 34357080, 2021). "Thus, we cannot identify the Smad1 role in p75NTR upregulation of BMP7 stimulation in human LN18 glioblastoma cells." (PMID 34357080, 2021). "Next, we determined whether p75NTR plays a role in BMP7-promoted human LN18 glioblastoma cell transmigration and migration." (PMID 34357080, 2021). "Our present study further demonstrated that the transmigration- and migration-stimulating effect of BMP7 on human LN18/LN229 glioblastoma cells might be through the autocrine stimulation." (PMID 34357080, 2021). "Based on this interesting finding, the present study further found that the endogenous and exogenous BMP7 stimulations indeed have an important role to promote the transmigration and migration capabilities of glioblastoma in human LN18/LN229 glioblastoma cells through Smad5-p75NTR pathway." (PMID 34357080, 2021). "In addition to the tumorigenicity-suppressing activity, bone morphogenetic protein 7 (BMP7) has recently been found for its invasion-promoting role in glioblastoma." (PMID 34357080, 2021). "In the present study, our result also elucidated that BMP7 could increase p75NTR expression to modulate glioblastoma cell transmigration and migration." (PMID 34357080, 2021). "Finally, we determined whether Smad5 and p75NTR are involved in regulating the BMP7 effect on human LN18 glioblastoma cell transmigration and migration." (PMID 34357080, 2021). "However, recently, it has been further indicated that BMP7 has another potential capability that could block the glioblastoma invasion through the Snail pathway." (PMID 34357080, 2021). "Additionally, BMP7 can suppress the tumorigenicity of stem-like glioblastoma cells." (PMID 34104086, 2021). "Similarly, a BMP-7 variant (BMP-7v) represses the proliferation of stem-like cells and the expression of stem cell markers and enhances the expression of differentiation marker in glioblastoma." (PMID 27661009, 2016). "Ad-Smad7 also inhibited activation of the BRE-luciferase reporter in these glioblastoma cell lines for both TGF-β and BMP7 stimulation, while additionally inhibiting TGF-β mediated activation of the CAGA12-luciferase reporter." (PMID 39724753, 2024). "BMP7 at 25 and 50 ng/mL significantly increased the transmigration level of human LN18 glioblastoma cells in a dose-dependent manner compared to the untreated controls." (PMID 34357080, 2021). "Our data therefore, suggest a potential therapeutic utility of BMP7, a neuroprotective agent in cerebral hypoxia/ischemia, combined with TMZ, for treating newly diagnosed glioblastoma or recurrent diseases exhibiting unmethylated MGMT." (PMID 26546412, 2015). "It was also shown that the BMP7 gene knockdown does not affect the cell viability of both glioblastoma cells." (PMID 34357080, 2021). "It was also shown that the BMP7 gene knockdown could significantly decrease the transmigration level and migration level of human LN18 and LN229 glioblastoma cells compared to the control-specific siRNA-transfected cells." (PMID 34357080, 2021). "In order to further clarify the decreased transmigration and migration levels induced by BMP7 gene knockdown were not because of the cell survival inhibition, the viability of both glioblastoma cells was determined by the MTT assay." (PMID 34357080, 2021). "In this community, BMP-7, as a ceRNA driven by MTAP, has been proved to act as a tumor suppressor that repressed proliferation, self-renewal, and tumor initiation of stem-like glioblastoma cells through suppressing epithelial–mesenchymal transition (EMT)." (PMID 31719831, 2019). "In addition, it was demonstrated that endogenous and exogenous BMP7 stimulation could increase the transmigration and migration capabilities of human LN18/LN229 glioblastoma cells." (PMID 34357080, 2021).
glioblastoma (continued). "Moreover, staining with an IgG negative control antibody showed the BMP7 antibody specificity in grade 4 glioblastoma tissue." (PMID 34357080, 2021). "Smad5 or p75NTR gene knockdown could significantly attenuate the transmigration level of human LN18 glioblastoma cells with and without BMP7 treatment." (PMID 34357080, 2021). "Indeed, exposure of glioblastoma stem-like cells to recombinant BMP7 in vitro increased SMAD1/5/8 phosphorylation, inhibited cell proliferation, stimulated glioblastoma differentiation, decreased neurosphere formation and attenuated expression of the stem-like genes Nanog, SOX2, Nestin and Olig2." (PMID 29799477, 2018). "Furthermore, p75NTR gene knockdown could also significantly attenuate the migration level of human LN18 glioblastoma cells with and without BMP7 treatment." (PMID 34357080, 2021).